ATF5 (activating transcription factor 5)
Diseases named in the same sentence as ATF5 in open-access papers (continued):
Sharing a sentence is not in itself a finding about the gene and the disease.
cancer (continued). "In addition, several other up-stream transcriptional factors can activate ATF5 expression, thereby promoting the expression of pro- and anti-survival target genes that regulate the cell survival pathways in cancer development and during cellular stress, inflammation, and metabolic maintenance." (PMID 35806136, 2022). "Thus, elucidating the mechanisms of ATF5 regulation under cellular stress could aid in the development of novel or enhanced cancer therapeutics." (PMID 32603335, 2020). "Therefore, understanding the relationship between the upregulation of ATF5 due to cellular stress inherent to cancer cells and the effects of ATF5 on tumor progression and metastasis could have great therapeutic potential." (PMID 32603335, 2020). "In addition, determining whether the functions of ATF5 in mitochondrial stress and the UPRmt are relevant to cancer development would be critical toward elucidation of ATF5 function in cancer." (PMID 29137451, 2017). "With the role of ATF5 in promoting survival in normal cells established, it could be hypothesized that dysregulation of ATF5 may serve as a survival factor in cancer." (PMID 29137451, 2017). "While a body of literature is already present on the function of ATF5 in cancer biology, notably in the regulation of survival and apoptosis, it will be interesting to explore the role of ATF5 in the context of UPRmt and cancer, particularly in EMT regulation and metastasis." (PMID 29250487, 2017). "First, we investigated whether ATF5 regulates radioresistance in human cancer cells." (PMID 25682872, 2015). "Thus, ATF5 expression and radioresistance are dependent on the cell cycle in cancer cells." (PMID 25682872, 2015). "Therefore, inhibition of ATF5 may be an effective way to enhance radiosensitivity in cancer cells and prevent the recurrence and progression of cancer after radiotherapy." (PMID 25682872, 2015). "Therefore, we examined the phenotypes of P and IR cells to determine whether ATF5 promotes malignancy in cancer cells." (PMID 25682872, 2015). "Therefore, ATF5 enhances invasiveness in cancer cells in vitro and in vivo." (PMID 25682872, 2015). "Finally, it is worth noting that the genome-wide RNAi negative-selection screening approach used to identify components of the ATF5-mediated survival pathway represents a general strategy that can be applied to identify essential survival pathways in other types of cancer cells." (PMID 21311102, 2010). "Our findings show that pre-treatment with Dpep, a cell-penetrating peptide designed to target the transcription factors ATF5, CEBPB, and CEBPD, sensitizes a variety of cultured cancer cells to the cytotoxic activity of NK-92MI cells." (PMID 40358191, 2025). "ATF5 upregulates tumorigenic genes, promoting cancer cell proliferation and invasion, while HSF1 helps cancer cells evade immune surveillance." (PMID 40680837, 2025). "Immunoprecipitation analysis revealed that ATF5 binds to MYC in KP4 cells on both stiff and soft ECMs, suggesting that in cancer cells on stiff ECMs, highly expressed MYC binds to ATF5 and localizes to the nuclei with ATF5." (PMID 40124511, 2025). "Collectively, these results indicated that stiff ECMs activate JAK signaling, leading to the formation of ATF5-MYC complexes in nuclei, thereby preventing EGR1 transcription in cancer cells." (PMID 40124511, 2025). "The cell-penetrating ATF5/CEBPB/CEBPD inhibitor peptide Dpep upregulates TXNIP mRNA and protein in the majority of cancer cell lines surveyed." (PMID 38920655, 2024). "In consonance with past reports cited above in which interference with ATF5, CEBPB or CEBPD expression suppressed migration of cancer cells." (PMID 36831248, 2023). "In this review, we relate how ATF5 and then CEBPB and CEBPD were identified as targets for treatment of brain and other cancers." (PMID 36831248, 2023).
cancer (continued). "As will be discussed here, the leucine zippers of ATF5, CEBPB and CEBPD are key features in the design of cell-penetrating decoy peptides to target them for brain and other cancers." (PMID 36831248, 2023). "The transcription factor activating transcription factor 5 (ATF5) regulates the gene expression of HSP60, GRP75 (mtHSP70) and other proteases for cancer cell survival and resistance against therapeutics and apoptosis." (PMID 36154922, 2022). "Mechanistically, ATF5 transcriptionally upregulates the expression of antiapoptotic proteins BCL2 and MCL1, hindering the apoptosis of cancer cells and reducing their chemosensitivity." (PMID 35180892, 2022). "The gene-regulatory factors ATF5, CEBPB and CEBPD promote survival, growth, metastasis and treatment resistance of a range of cancer cell types." (PMID 34065488, 2021). "Together, these findings indicate that Bpep/Dpep reduce expression of well-defined ATF5, CEBPB and CEBPD targets with cancer relevance." (PMID 34065488, 2021). "A copious amount of literature links basic leucine zipper transcription factors, ATF5, CEBPB and CEBPD, to tumor formation, growth, metastasis and treatment resistance in a variety of cancers." (PMID 34065488, 2021). "ATF-5 has been reported to regulate expression of Egr-1, BCL-2, and MCL1 to mediate proliferation and survival in cancer." (PMID 34630117, 2021). "Activating transcription factor 5 (ATF5) facilitates the expression of various genes and has been extensively studied for its potential role in cancer treatment." (PMID 33980247, 2021). "In the process of UPRmt, various components are activitated to enhance the mitochondria-nucleus retrograde signaling to promote carcinoma progression, including hypoxia-inducible factor (HIF), activating transcription factor ATF-4, ATF-5, CHOP, AKT, AMPK." (PMID 34717757, 2021). "Six genes were selected as tumor suppressor gene candidates, among which, ECM1, ATF5 and EOMES are confirmed via siRNA experiments to have potential anti-cancer functions." (PMID 25517360, 2014). "ATF5 modulates many genes’ expression and regulates the cell cycle, unfolded protein response (UPR), anti-apoptosis, immune, and other signaling pathways, playing a crucial role in the survival and proliferation of cancer cells." (PMID 40695891, 2025). "Additionally, H3K18 lactylation enhances METTL14, which deposits m6A on ATF5, suppressing the ATF5/WDR74/β-catenin axis and reducing cancer stem-like traits." (PMID 41373440, 2025). "In addition, ATF5 suppressed the expression of early growth response 1 (EGR1), thereby accelerating cancer cell proliferation." (PMID 40124511, 2025). "Furthermore, the localization of ATF5 in the nuclei suppressed the transcription of EGR1, a protein that prevents the proliferation of cancer cells." (PMID 40124511, 2025). "ATF5 induces the upregulation of antiapoptotic proteins such as Bcl-2 and MCL1, promoting tumor cell growth, and the upregulation of integrin-α2 and integrin-β1, which favors cancer cell invasion." (PMID 38882057, 2024). "There are many potential advantages of using combination treatments rather than monotherapies for cancer treatment, and findings thus far indicate that this is so for cell-penetrating ATF5, CEBPB and CEBPD decoy peptides." (PMID 36831248, 2023). "In addition, upregulation of ATF5 transcription by the BCR-ABL/PI3K/AKT/FOXO4 signaling pathway and CREB3L2 is responsible for the high expression level of ATF5 in cancer." (PMID 35180892, 2022). "Although highly probable, studies have not yet shown the ability of ATF5 to regulate the expression of UPRmt components in cancer." (PMID 35864539, 2022). "ATF5, CEBPB and CEBPD have been reported to contribute to cancer cell radiation resistance." (PMID 34065488, 2021). "However, cancer cells can become resistant to stress-induced apoptosis through upregulation of BCL-1 and MCL-2, both downstream targets of ATF5." (PMID 32603335, 2020).
cancer (continued). "Although survivin downregulation is sufficient to drive tumor cell death, survivin over-expression does not rescue cancer cells from dn-ATF5-promoted apoptosis." (PMID 31551409, 2019). "It was suggested the BCL-2 expression is regulated by ATF5 in cancer cells but not in non-transformed cells." (PMID 28785242, 2017). "The role of ATF5 in the transcriptional activation of proteins such as mTOR, BCL2, and MCL1 shows the importance of ATF5 in modulating activity of pathways critical to the development of cancer." (PMID 29137451, 2017). "In addition, ATF5 promotes the expression of integrin β1 and represses MRLC diphosphorylation, thereby increasing invasiveness in cancer cells." (PMID 25682872, 2015). "It is anticipated that a better understanding of the proximal transcriptional events triggered by cell-penetrating peptides that target ATF5, CEBPB and CEBPD will better define their mechanisms of action, which in turn will inform their best use in therapies for treatment of brain and other cancers." (PMID 36831248, 2023). "Furthermore, it is important to recognize that ATF5 is likely not the sole transcription factor responsible for the activation of UPRmt in cancer." (PMID 35864539, 2022). "Moreover, in a non-transcriptional role, ATF5 has been reported as a critical component of the centrosome, also of relevance to cancer cell survival/growth." (PMID 34065488, 2021). "In addition, other cancer-relevant proteins are potentially bound and sequestered by Bpep and Dpep, but not by dn-ATF5." (PMID 34065488, 2021). "Targeting ATF5 in anticancer therapy may be particularly attractive because of its differential role in cancer cells than in non-transformed cells, thus allowing specificity of the treatment." (PMID 28785242, 2017). "Interestingly, the attractiveness of ATF5 gene targeting as an anticancer therapy also emanates from its differential role in cancer cells than in non-transformed cells." (PMID 28785242, 2017). "Although this is intriguing, no studies have been conducted assessing whether ATF5 promotes cancer development via its centrosomal function." (PMID 29137451, 2017). "Thus, ATF5 is not consistently expressed but changes according to the cell cycle phase in cancer cells." (PMID 25682872, 2015). "Furthermore, previous studies have indicated that repression of ATF5 induces cancer cell death and that ATF5 inhibition does not affect the viability of non-cancerous neural and breast cells." (PMID 25682872, 2015). "Therefore, ATF5 might be blocked in HCC, resulting in anti-apoptotic effects and cancer cell survival." (PMID 25517360, 2014). "In particular, we identified three new genes (ECM1, ATF5, and EOMES) with potential anti-cancer functions that may promote the understanding of the molecular mechanisms of HCC development and progression and potentiate the future clinical applications of 5hmC detection." (PMID 25517360, 2014). "Similarly, a query of the Oncomine cancer profiling database revealed that, in general, the expression level of ATF5 is significantly higher in malignant tissues than their normal counterpart tissues." (PMID 21311102, 2010). "Consistent with this paradigm, a number of studies have demonstrated that ATF5 is highly expressed in a variety of cancer cell types, whereas it is not detectably expressed in most normal human tissues (the exceptions being the liver, prostate and testis, where ATF5 is expressed at a high level)." (PMID 21311102, 2010). "Furthermore, ATF5 shows pronounced sequence homology with ATF4 and shares similar modes of regulation and downstream effects i.e. both are regulated translationally via stress-responsive inhibitory uORFs and modulate processes involved in tissue development, apoptosis, and cancer." (PMID 29137451, 2017).
cancer (continued). "We have developed cell-penetrating peptides that target the transcription factors ATF5, CEBPB, and CEBPD and that promote apoptotic cancer cell death both in vitro and in vivo without apparent toxicity to non-transformed cells." (PMID 40358191, 2025). "We have designed cell-penetrating peptides that target the leucine zipper transcription factors ATF5, CEBPB and CEBPD and that promote apoptotic death of a wide range of cancer cell types, but not normal cells, in vitro and in vivo." (PMID 38920655, 2024).
tumor (43 papers, 2010 to 2026). "When expressed in tumor cells in vitro or in vivo, dn-ATF5 promotes their apoptotic death and causes tumor regression." (PMID 31551409, 2019). "Activating transcription factor 5 (ATF5) is a novel factor that is closely associated with tumor cell differentiation, proliferation and apoptosis." (PMID 25120656, 2014). "ATF5 belongs to the bZIP family of transcription factors and has been implicated in the regulation of differentiation, protection from various cellular stresses, and tumor cell survival." (PMID 38014922, 2023). "ATF5 has been implicated in tumor development by transcriptional regulation of downstream genes." (PMID 38223508, 2023). "Moreover, low levels of ATF5 have been associated with increased tumor malignancy and can be used as a prognostic indicator in HCC." (PMID 35806136, 2022). "Correlation analysis between DVL1 and ATF5 suggests a regulatory interaction, potentially impacting tumor progression." (PMID 40276499, 2025). "It is noteworthy that TRMT112 plays a crucial role in the m7G methylation process, which has been confirmed to promote the transcription of ATF5, thereby driving tumor occurrence and progression." (PMID 41235342, 2025). "high PLP2+ Tumor EPCs score group highly expressed ATF6, ELF1, ERG and PLAGL1 genes, while low PLP2+ Tumor EPCs score group highly expressed ATF5, TBX21, SPIB, LHX2 and JUND genes." (PMID 38482016, 2024). "Total RNA was purified from IDH1mut (n = 12) and IDH1wt (n = 12) patient tumor samples and subjected to direct ATF5 qRT-PCR and m6A-RNA immunoprecipitated ATF5 qRT-PCR." (PMID 38445960, 2024). "In m6A-immunoprecipitated RNA fractions, there was significantly more m6A enrichment in ATF5 transcripts isolated from IDH1mut versus IDH1wt patient tumor samples (P ≤ 0.05)." (PMID 38445960, 2024). "We also demonstrated that targeting ATF5 using a cell-penetrating dominant-negative ATF5 peptide inhibitor (CP-d/n-ATF5) increased the anoikis sensitivity of tumor cells and inhibited metastasis." (PMID 38014922, 2023). "In conclusion, our results revealed the tumor-specific upregulation of the transcription factor ATF5, which positively correlated with worse treatment responses." (PMID 38223508, 2023). "Conversely, ATF5 overexpression protects tumor cells from apoptotic stimuli and promotes treatment resistance." (PMID 38014922, 2023). "It was noted that while the extent of tumor resection and temozolomide treatment was similar for both groups, the high ATF5 group was significantly older." (PMID 36831248, 2023). "We noticed that the suppression of tumor survival induced by ATF5 knockdown was more prominent in semisolid cultures and xenograft models than in liquid cultures." (PMID 38223508, 2023). "ATF5 was significantly expressed on Mono/Macro and pDC subgroups in tumor cells, whereas C1orf53 was predominantly expressed on Mono/Macro subgroup and SMARCD3 was predominantly expressed on Mast subgroup." (PMID 37859813, 2023). "Considering the relatively specific expression of ATF5 in malignant T cells, we evaluated the clinical relevance of ATF5 expression in a cohort of 49 tumor-stage CTCL patients with bulk RNA sequencing data which was published by our group previously." (PMID 38223508, 2023). "The effect of ATF5 knockdown on liver and bone marrow metastasis and circulating tumor cells (CTC) was also examined." (PMID 38014922, 2023). "It is clear from the literature reviewed above that a major response of brain and other tumor cells to ATF5, CEBPB and CEBPD knockdown or interference with activity is the appearance of apoptotic cell death." (PMID 36831248, 2023). "CP-d/n-ATF5 also showed in vivo efficacy by inhibiting tumor growth, reducing CTC survival, and preventing metastatic progression." (PMID 38014922, 2023). "We report that ATF5 increases tumor cell survival in circulation by inducing anoikis resistance in vitro and in vivo, thereby facilitating metastasis." (PMID 38014922, 2023).